DPP4 (dipeptidyl peptidase 4)
Diseases named in the same sentence as DPP4 in open-access papers (continued):
Sharing a sentence is not in itself a finding about the gene and the disease.
endotoxemia (12 papers, 2011 to 2025). "Our previous studies also showed that genetic deficiency of DPP4 in rats improved cardiac function during endotoxemia and ischemia/reperfusion, which were partly associated with GLP-1 signaling." (PMID 23359639, 2013). "We have demonstrated that DPP4-deficient rats possess resistance to endotoxemia and ischemia/reperfusion stress." (PMID 23359639, 2013). "DPP-4-deficient rats had a better preservation of cardiovascular function than wild-type rats during endotoxemia, which correlated with a more prominent elevation of GLP-1 signaling." (PMID 22125632, 2011). "Treatment of DPP4 inhibitor (gliptin) decreases dendritic cell maturation upon LPS-induced endotoxemia." (PMID 30934882, 2019). "In another study, our group demonstrated that DPP-4 inhibition by linagliptin, GLP-1 supplementation by liraglutide, and genetic deletion of DPP-4 improve survival of LPS-induced endotoxemia in mice." (PMID 31341533, 2019). "On the other hand, endotoxemia induces upregulation of DPP-4 expression in vascular endothelial cells, and DPP-4 inhibitors are reported to act as vascular endothelial protectors." (PMID 29037205, 2017). "After LPS-induced sepsis in rats with DPP-4 knockout, the administration of GLP-1 RAs can increase cardiac cAMP levels, improve cardiovascular function in animals with endotoxemia, and improve the prognosis of endotoxemia." (PMID 34335269, 2021). "Moreover, DPP-4 inhibition by the gliptins, linagliptin, sitagliptin, and liraglutide, as well DPP-4 KO, improved survival, vascular inflammation, and vascular dysfunction in an animal model of LPS-induced endotoxemia." (PMID 34205264, 2021).
liver cirrhosis (12 papers, 2010 to 2025). "PIGR is a particularly promising protein as its association with NAFLD and liver cirrhosis is novel, and its levels in plasma are highly correlated with DPP4, a widely used drug target in the treatment of T2D." (PMID 30824564, 2019). "We conducted a retrospective cohort study to determine the long-term outcomes of DPP-4 inhibitors use in patients with T2D and compensated liver cirrhosis." (PMID 35252271, 2022). "The pharmacokinetic and safety profiles of DPP-4 inhibitors are generally good in patients with compensated liver cirrhosis, but data on patients with decompensated liver cirrhosis are limited." (PMID 35252271, 2022). "In contrast, DPP4 is downregulated in tissues of liver cirrhosis, endometrial adenocarcinoma tissues, and a low serum level of DPP4 was related to a poor prognosis for patients who have esophageal squamous cell carcinoma." (PMID 32294701, 2020). "They found that the subjects treated with GLP-1RAs, compared with those undergoing DPP-4 inhibitors, did not have a lower risk of developing liver cirrhosis, while patients treated with SGLT-2 inhibitors had a lower risk of liver cirrhosis compared to those undergoing DPP-4 inhibitors." (PMID 41011192, 2025). "DPP-4 inhibitors may be useful in patients with NAFLD and chronic liver disease, but the patients must be monitored for cirrhotic decompensation and hepatic failure in patients with liver cirrhosis." (PMID 35252271, 2022).
metastatic disease (12 papers, 2012 to 2025). "In addition to the analysis of DPP4 expression level, decreased DPP4 enzymatic activity was observed in serum samples of PCa patients with metastatic disease compared to patients with localized disease." (PMID 37533175, 2023).
non-alcoholic steatohepatitis (12 papers, 2010 to 2025). "DPP4 is ubiquitously expressed, and its hepatic DPP4 expression is upregulated under non-alcoholic steatohepatitis (NASH) conditions." (PMID 33173107, 2020). "This has led to the hypothesis that inhibiting DPP-4 could potentially improve the histological characteristics of MASLD and MASH (non-alcoholic steatohepatitis) by preserving GLP-1’s beneficial actions." (PMID 40244398, 2025). "Also, all major complications of experimental nonalcoholic fatty liver disease (NAFLD) and nonalcoholic steatohepatitis (NASH), namely, hepatic and vascular inflammation, were improved by DPP-4 inhibitor therapy by linagliptin and sitagliptin." (PMID 31341533, 2019). "DPP-4 inhibitors may be effective for the treatment of NAFLD and may be able to prevent its progression to non-alcoholic steatohepatitis." (PMID 26670228, 2015).
Arthritis (11 papers, 2006 to 2026). Inflammation of a joint. "Specifically, we assayed if these CD47Hi and CD47Lo sub-populations expressed ITGA5 and/or DPP4/CD26 as these markers have previously been associated with stromal progenitors and shown to play a role in the progression of arthritis." (PMID 41557734, 2026). "DPP-4 inhibitors have been associated with arthritis and arthralgia regardless of the specific agent used, suggesting a possible class effect." (PMID 41302503, 2025). "Studies indicate that inhibitors of DPP-4 may be involved in the development of arthritis." (PMID 41302503, 2025). "Metformin, TZDs, DPP-4 inhibitors and GLP-1 analogues may exert an immunomodulatory action downregulating the expression of proinflammatory cytokines and chemokines, thus reducing synovial inflammation and potentially leading to improvement of arthritis." (PMID 33995414, 2021). "DPP4 was only found to be related to type 2 diabetes mellitus rather than in arthritis development." (PMID 34869404, 2021).
chronic myeloid leukemia (11 papers, 2016 to 2025). "DPP4 targeting CAR-T cells were developed to target DPP4+ leukemic stem cells in chronic myeloid leukaemia (CML)." (PMID 35158891, 2022).
acute lymphoblastic leukemia (10 papers, 2009 to 2021). Leukemia with an acute onset, characterized by the presence of lymphoblasts in the bone marrow and the peripheral blood. "CD26/DPP4 is expressed on aggressive T-cell hematological malignancies such as T-cell lymphoblastic lymphoma (T-LBL) and T-cell acute lymphoblastic leukemia (T-ALL) and was associated with poor survival." (PMID 34885056, 2021).
Autoimmunity (10 papers, 2012 to 2025). The occurrence of an immune reaction against the organism's own cells or tissues. "Given that low serum DPP4 levels have been linked to increased susceptibility of autoimmune conditions, we propose that carriers of the T allele may already have diminished enzymatic activity." (PMID 41373842, 2025). "The enzymatic CD26/DPP4 activity in serum has been mainly attributed to soluble sCD26 and serum levels of DPP4 activity and/or sCD26 protein were associated with diverse diseases including autoimmunity, infections, autoimmunity, and malignancies." (PMID 34885056, 2021). "CD26/DPP4 is a membrane-associated exopeptidase that by engaging inhibitory ligands may limit autoimmunity in mice by regulating Th1 responses, and by hydrolyzing substrates CXCL12 and CCL5." (PMID 31829262, 2019). "Although the mechanisms by which DPP4 inhibition contributes to BP pathogenesis remain unclear, it has been hypothesized that gliptins may alter the antigenic integrity of the epidermal basement membrane, thereby promoting autoimmunity in genetically susceptible individuals." (PMID 41373842, 2025). "Moreover, in new-onset diabetic mice as an in vivo model system for autoimmunity DPP4 inhibition increased the proportion of T regulatory cells and even reversed the disease." (PMID 34885056, 2021).
liver cancer (10 papers, 2020 to 2026). An epithelial or non-epithelial malignant neoplasm that arises from the liver. "For example, overexpression of DPP4 was associated with prolonged survival of patients with kidney, lung, or liver cancers." (PMID 35141230, 2021). "In cancer patients with metabolic disorders, HMGCL regulates H3K9 acetylation through β-OHB and modulates the expression of dipeptidyl peptidase-4 (DPP4) in a dose-dependent manner, leading to ferroptosis in liver cancer cells." (PMID 41513612, 2026). "Moreover, high expression of the DPP-4 enzyme may contribute to the progression of liver cancer." (PMID 40786041, 2025). "To further investigate DPP4 gene family expression in liver cancer prognosis, we stratified DPP9, DPP8 and DPP4 based on median expression in HCC." (PMID 33915844, 2021). "Studies on DPP-4 enzyme and its role in liver cancer development still did not provide a conclusive answer regarding its role in HCC." (PMID 40786041, 2025).
neuropathy (10 papers, 2014 to 2025). A disorder affecting the nervous system that manifests with pain, tingling, numbness, and/or muscle weakness. "At grade 0 (intact skin), progression to the superficial ulcer (Grade 1) or deeper involvement of bones and tendons (Grade 2), caused by trauma or neuropathy, can often be prevented through early treatment with antihyperglycemic medications (e.g., DPP4 inhibitors, GLP-1 receptor agonists)." (PMID 40725154, 2025). "Our results indicate the contribution of the DPP4 to the development and maintenance of mechanical hyperalgesia in this model of neuropathy, but the underlying mechanisms are unknown." (PMID 29472575, 2018). "This suggests that DPP4 contributes to the development of hyperalgesia also in neuropathy, and the key player is microglia." (PMID 36674439, 2023). "High resolution confocal laser scanning imaging revealed that neuronal DPP4 was typically confined to presynaptic, and also to somatic domains, with significantly decreased densities in neuropathy." (PMID 29472575, 2018). "Microglia and astrocytes expressed DPP4 with one and two orders of magnitude higher than neurons, respectively, and DPP4 expression significantly increased in astrocytes during carrageenan-induced peripheral inflammation and in microglia in neuropathy." (PMID 36674439, 2023). "Moreover, the absence of large randomized clinical studies tackling the effects of DPP-4 inhibitors on diabetic neuropathy in the long term makes drawing conclusions about the benefits of DPP-4 inhibitors on neuropathy too preliminary at this point." (PMID 32190049, 2020). "DPP4 significantly increased in astrocytes during inflammation and in microglia in neuropathy." (PMID 29472575, 2018). "Comparing the extent of the antihyperalgesic effect of DPP4 inhibitors in inflammation and neuropathy may suggest that DPP4 inhibitors are more effective in inflammatory conditions then in neuropatic states." (PMID 29472575, 2018). "Antihyperglycemic agents such as DPP-4 inhibitors (e.g., teneligliptin) and GLP-1 receptor agonists (e.g., liraglutide, semaglutide) have been shown to lessen the severity of neuropathy by improving nerve conduction and reducing oxidative stress." (PMID 40725154, 2025). "Similarly to the effects of ischemic injuries in the brain, our q-PCR and in situ hybridization analysis showed that DPP4 mRNA level was not influenced by inflammation or neuropathy in the spinal dorsal horn." (PMID 29472575, 2018). "In contrast to DPP4 mRNA, the overall amount of DPP4 protein detected by Western-blot and immunohistochemistry significantly increased in the spinal dorsal horn during inflammation and did not change in neuropathy compared to the physiological state." (PMID 29472575, 2018). "Spinal administration of DPP4 inhibitor IPI significantly decreased the hyperalgesia provoked by the intraplantar injection of carrageenan or partial nerve ligation, which could be eliminated by general opioid antagonist NTX and the selective MOR antagonist CTAP in inflammation but not neuropathy." (PMID 36674439, 2023).
prediabetes (10 papers, 2014 to 2026). "Several lines of evidence suggest that incretin-based therapies, including GLP-1 receptor agonists and dipeptidyl peptidase-4 inhibitors, may stabilize or reverse the β-cell loss and slow or prevent the progression of prediabetes." (PMID 34025574, 2021). "Nonetheless, our study provides the first evaluation of the effect of DPP-4 inhibitors on GM composition in humans with prediabetes." (PMID 38678119, 2024). "Regardless of the glucose tolerance status (normal glucose tolerance, prediabetes, or T2DM), a 4-year longitudinal study showed that baseline DPP4 activity and GLP-1 were negatively associated." (PMID 26146634, 2015). "In fact, the possibility of using incretin modulators, including (but not only) DPP-4 inhibitors, in prediabetes is also under debate." (PMID 26075286, 2015). "In summary, our data indicate that DPP4 genetic polymorphisms are involved in the control of post-OGTT excursions and subsequent C-peptide release responses through glucose-sensing mechanisms that are abrogated in prediabetes." (PMID 35190847, 2022). "The hypothesis that the changes in incretins in prediabetes are directly related to DPP4 seems to be a plausible one." (PMID 26146634, 2015). "Gal-4 facilitates the transport of dipeptidyl peptidase-4 (DPP-4) to the intestinal epithelium, leading to decreased incretin activity and contributing to impaired insulin secretion, prediabetes and its cardiometabolic complications." (PMID 41226378, 2025). "The projected cost of metformin treatment for seven patients with prediabetes can avoid the cost of treating a non-complicated diabetic patient with metformin + glimepiride after 2.9 years; with metformin + DPP4 inhibitors after 2.6 years; and with metformin + insulin after 1.9 years." (PMID 31410086, 2017).
upper respiratory tract infection (10 papers, 2010 to 2024). "Additionally, DPP-4 inhibitors are associated with a higher risk of infections, especially upper respiratory tract infections." (PMID 39121166, 2024). "Our study on ACE2 provides a systematic road map to redesigning an entry receptor as a therapeutic, and we believe the same strategy could be applied to other entry receptors such as DPP4 for treating MERS and ANPEP for treating upper respiratory tract infections by HCoV-229E." (PMID 32766586, 2020). "Our study on ACE2 provides a systematic road map to redesigning an entry receptor as a therapeutic, and we believe the same strategy could be applied to other entry receptors such as DPP4 for treating MERS and aminopeptidase N (ANPEP) for treating upper respiratory tract infections by HCoV-229E." (PMID 33093202, 2020).
Anxiety (9 papers, 2017 to 2025). Intense feelings of nervousness, tension, or panic often arise in response to interpersonal stresses. "Additional insights come from studies on DPP4-deficient rodents, which show enhanced extinction of cued fear, reduced anxiety-like behavior [29, but see 30] and reduced depressive-like behavior." (PMID 40490517, 2025). "After exclusion of subjects taking DPP4-inhibitors the association of PP and anxiety in the male subgroup remained significant (r = 0.427, p = 0.008)." (PMID 33192409, 2020). "After excluding subjects taking DPP4 inhibitors association of PP and anxiety remained significant which concurs well with previous results that found PP secretion to be unaffected by DPP4 inhibition." (PMID 33192409, 2020). "Our findings contribute to the growing body of evidence supporting the therapeutic potential of DPP4 inhibition in alleviating symptoms of anxiety and mood disorders." (PMID 40490517, 2025). "Preclinical studies suggest that DPP4 inhibition may offer potential benefits for treating conditioned fear, anxiety and mood disorders." (PMID 40490517, 2025). "Both the newly identified DPP4, previously linked to schizophrenia and brain dysfunction, and TRHR, previously linked to neuronal hyperexcitability, seizures, and anxiety may be linked to ASD in our cohort." (PMID 28358038, 2017). "However, anxiety has also been found to inhibit DPP4 levels." (PMID 40766923, 2025). "GLP1-RA users that took metformin, sulfonylurea and oral medication combination had lower risk of anxiety, so as to those that did not use TZD, acarbose, SGLT2 inhibitors, DPP4 inhibitors, or insulin." (PMID 35281896, 2022).
cardiac hypertrophy (9 papers, 2014 to 2025). "Despite these molecular changes, cardiac hypertrophy and systolic and diastolic function were unchanged with systemic and organ‐specific loss of Dpp4." (PMID 40771104, 2025). "Studies have shown that chronic exposure to restraint stress causes increased DPP4 levels, weight loss, and cardiac hypertrophy." (PMID 39968759, 2025). "Recently a preclinical study has reported that diabetic mice treated with Dpp4 inhibitor exhibited modest cardiac hypertrophy, impairment of cardiac function, and dysregulated expression of genes and proteins controlling inflammation and cardiac fibrosis." (PMID 27496100, 2016). "Finally, It is necessary to understand the role of DPP4 itself in cardiac hypertrophy to address the potential role of DPP4 inhibitors as therapeutics." (PMID 24521405, 2014). "DPP4−/− mice showed improved survival after experimental infarction, and treatment with 250 mg/kg/d sitagliptin for 8 weeks led to improved functional recovery after ischemia/reperfusion (I/R) injury through increased endothelial cell density, reduced myocardial hypertrophy and enhanced fibrosis." (PMID 34389003, 2021). "A recent study reported that genetic deficiency of DPP4 improve cardiac function, whereas chemical inhibition of DPP4 by MK-0626 induced cardiac hypertrophy and impaired cardiac function, indicating drug related unspecific effects might negatively impact cardiac function." (PMID 28619058, 2017).
Cerebral ischemia (9 papers, 2012 to 2024). Restriction of arterial blood supply to the brain associated with insufficient oxygenation to support the metabolic requirements of the tissue. "Linagliptin, a dipeptidyl peptidase-4 (DPP-4) inhibitor, has demonstrated promising neuroprotection against cerebral ischemia and diabetic dementia." (PMID 37630980, 2023). "The serum DPP4 activity in the group of patients with cerebral ischemia was significantly higher than the control group." (PMID 36829868, 2023). "Considering the serum DPP4 activity in neonates with different neurological symptomatology: among the full-term neonates with cerebral ischemia, the maximum DPP4 activity was found in the group with an excitement syndrome." (PMID 36829868, 2023). "DPP4 mRNA was detected in cortical areas in adult naïve animals and its level did not change after cerebral ischemia." (PMID 29472575, 2018). "Notably, whereas DPP-4 immunoreactivity is generally not found in naïve adult brain, its expression is time-dependently seen in microglia, astrocytes and neurons following cerebral ischemia." (PMID 38563864, 2024).
chronic hepatitis C (9 papers, 2010 to 2024). "Pretreatment serum levels of interferon-γ-inducible protein-10 (IP-10, CXCL10) and dipeptidyl peptidase-4 (DPP IV) predict treatment response in chronic hepatitis C (CHC)." (PMID 26339796, 2015). "Motivated by the ability to regulate lymphocyte trafficking in vivo, we conducted two prospective clinical trials to test the effects of DPP4 inhibition on CXCL10 processing in healthy donors and in chronic hepatitis C patients, a disease in which DPP4 levels are found to be elevated." (PMID 27137491, 2016). "Moreover, DPP4 activity levels did not correlate with other markers of bile duct or hepatocyte injury in chronic hepatitis C and other liver viral infections." (PMID 39001488, 2024).
hypertriglyceridemia (9 papers, 2011 to 2024). A laboratory test result indicating elevated triglyceride concentration in the blood. "DPP-4 inhibitors improve postprandial hypertriglyceridemia, so DPP-4 inhibitors could decrease oxLDL levels by increasing the size and density of LDL-C." (PMID 25995772, 2015). "In this regard, DPP4 antagonists and pemafibrate have the potential to benefit even “lean” NAFLD patients with T2DM and hypertriglyceridemia." (PMID 34943553, 2021). "This independent relationship between DPP4 activity and impaired cognitive function still existed in a subgroup of participants without hyperuricemia and hypertriglyceridemia." (PMID 28798686, 2017).